GSTA3 (glutathione S-transferase alpha 3)
Description:
Conjugation of reduced glutathione to a wide number of exogenous and endogenous hydrophobic electrophiles. Catalyzes isomerization reactions that contribute to the biosynthesis of steroid hormones. Efficiently catalyze obligatory double-bond isomerizations of delta(5)-androstene-3,17-dione and delta(5)-pregnene-3,20-dione, precursors to testosterone and progesterone, respectively. Has substantial activity toward aflatoxin B1-8,9-epoxide (By similarity).
Synonyms: GSTA3-3; GTA3
Tractability: Small molecule: it has a high-quality binding pocket. PROTAC: ubiquitination databases record sites on it.
Target class: Enzyme; Transferase
Gene: Protein-coding gene on chromosome 6 (52,896,639 to 52,909,701, reverse strand). Ensembl gene ENSG00000174156.
Subcellular location: Cytoplasm
Subcellular location (Human Protein Atlas): Cytosol
Pathways (Reactome):
Cellular responses to stimuli: NFE2L2 regulating anti-oxidant/detoxification enzymes
Metabolism: Glutathione conjugation
Gene Ontology:
Molecular function: glutathione transferase activity; steroid Delta-isomerase activity
Biological process: glutathione metabolic process; xenobiotic metabolic process
Cellular component: cytosol; extracellular exosome; cytoplasm
Genetic constraint (gnomAD): Loss-of-function variants: 12 observed, 16.56 expected, observed/expected ratio (o/e) 0.72, 90% interval 0.46 to 1.17. The synonymous counts are far from expectation, so gnomAD's model fits this gene poorly and the ratio says little. Missense variants: 248 observed, 217.12 expected, observed/expected ratio (o/e) 1.14, 90% interval 1.03 to 1.27. Synonymous variants: 99 observed, 76.15 expected, observed/expected ratio (o/e) 1.3, 90% interval 1.1 to 1.54.
Homologues: Orthologues: chimpanzee GSTA3 (85% identical), macaque GSTA2 (77% identical), zebrafish gstp1.1 (32% identical), tropical clawed frog gstp1 (30% identical), Caenorhabditis elegans gst-37 (28% identical), Caenorhabditis elegans gst-23 (28% identical), Caenorhabditis elegans gst-39 (28% identical), Caenorhabditis elegans gst-29 (27% identical), Caenorhabditis elegans gst-3 (27% identical), Caenorhabditis elegans W10C8.4 (26% identical), Caenorhabditis elegans gst-1 (26% identical), Caenorhabditis elegans gst-32 (26% identical), and 31 more. Paralogues in human: GSTA1 (91% identical), GSTA2 (89% identical), GSTA5 (86% identical), GSTA4 (53% identical), GSTP1 (31% identical), GSTM2 (26% identical), GSTM1 (25% identical), GSTM3 (24% identical), GSTM4 (24% identical), GSTM5 (23% identical), HPGDS (22% identical).
Diseases named in the same sentence as GSTA3 in open-access papers:
GSTA3 is named in the same sentence as 26 diseases in open-access papers, as found by Europe PMC text mining. Sharing a sentence is not in itself a finding about the gene and the disease. The quoted sentences say what the papers report.
liver fibrosis (9 papers, 2016 to 2023). "Moreover, four potential cis-acting targets associated with hepatic fibrosis were identified as labeled by Gsta3, Met, Nox4, and Pdgfd, and their reliability was confirmed by validation experiments." (PMID 34597331, 2021). "Therefore, the present study was designed to verify whether GSTA3 is involved in liver fibrosis, elucidate the underlying mechanisms and then prove whether AKF-PD reduces liver fibrosis by regulating GSTA3." (PMID 31443720, 2019). "Currently, our findings have identified the heat shock protein, phosphorylation-associated enzymes or kinases, Sm16, GSTA3, MMP7, GPCRs, EF1-α, and other protein components that have been associated with schistosome-induced liver fibrosis." (PMID 36986363, 2023). "Our results have identified heat shock proteins, phosphorylation-associated enzymes, or kinases, such as Sm16, GSTA3, GPCRs, EF1-α, MMP7, and other proteins linked to schistosome-induced liver fibrosis." (PMID 36986363, 2023). "GSTA3 inhibited hepatic stellate cells (HSCs) activation and liver fibrosis through suppression of the MAPK and GSK-3β signaling pathways by regulating OS." (PMID 38069262, 2023). "Collectively, AKF-PD relieved liver fibrosis partially by upregulating GSTA3 expression and negatively regulating oxidative stress and its downstream pathways." (PMID 31443720, 2019). "We demonstrated firstly that GSTA3 inhibited HSCs activation and liver fibrosis through suppression of the MAPK and GSK-3β signaling pathways." (PMID 31443720, 2019). "AKF-PD alleviated rat hepatic fibrosis and potently inhibited HSCs activation correlated with restoring GSTA3." (PMID 31443720, 2019). "Some studies reported that GSTA3 has been playing an important role in development of kidney fibrosis and liver fibrosis via mediating through oxidative stress pathway." (PMID 30005088, 2018). "As a recently we developed water-soluble pyridone agent with antifibrotic features, fluorofenidone (AKF-PD) can attenuate liver fibrosis, present studies were designed to explore the role of GSTA3 in liver fibrosis and its modulation by AKF-PD in vivo and in vitro." (PMID 31443720, 2019). "Glutathione S-transferase A3 (GSTA3) is known as an antioxidative protease, however, the crucial role of GSTA3 in liver fibrosis remains unclear." (PMID 31443720, 2019). "Considering the crucial role of oxidative stress in HSC activation and liver fibrosis, we speculate that GSTA3 may play a unique role in liver fibrosis." (PMID 31443720, 2019). "It was reported that extensive liver fibrosis are observed in GSTA3 knockout mice, suggesting that GSTA3 may be critical for protecting mice from liver fibrosis." (PMID 27602565, 2016). "In the future, GSTA3 may be developed as a potent therapeutic target for liver fibrosis." (PMID 31443720, 2019). "Our investigation revealed that GSTA3 has unexpected new functions in the inhibition of HSC activation and hepatic fibrosis for the first time." (PMID 31443720, 2019). "We detected GSTA3 expression in two HSC cell lines, CFSC-2G and LX2, to confirm the participation of GSTA3 in liver fibrosis." (PMID 31443720, 2019). "GSTA3 inhibits HSC activation and liver fibrosis by inhibiting MAPK and GSK-3 β signalling pathways, suggesting that GSTA3 could be a feasible target for therapeutic interventions for liver fibrosis." (PMID 33024640, 2020). "Thus, GSTA3 is involved in HSC activation and liver fibrosis by regulating oxidative stress." (PMID 31443720, 2019). "However, the pathophysiological role of GSTA3 in liver fibrosis has not been studied." (PMID 31443720, 2019).
gastric cancer (2 papers, 2020 to 2022). A primary or metastatic malignant neoplasm involving the stomach. "Previous studies have alluded to GSTA3’s involvement in tumorigenesis in colon cancer and gastric cancer as higher expression translated into poorer survival outcomes." (PMID 36428698, 2022).
melanoma (2 papers, 2022 to 2024). A malignant, usually aggressive tumor composed of atypical, neoplastic melanocytes. "The study suggests that GSTA3 plays a significant role in the effectiveness of immune checkpoint inhibitors in treating melanoma and implies the potential of GSTA3 as a genomic biomarker for predicting patient outcomes." (PMID 38791327, 2024). "In addition, GSTA3 was identified as one of the highest contributing features in the study on the genomic and transcriptomic predictors of response to immune checkpoint inhibitors in melanoma patients." (PMID 38791327, 2024). "Additionally, through transcriptomic data, we were able to identify novel genes (GSTA3 and VNN2) that could lead to better stratification of potential responders to ICIs in melanoma." (PMID 36428698, 2022).
renal fibrosis (2 papers, 2016 to 2023). A final common manifestation of a wide variety of chronic kidney diseases characterized by glomerulosclerosis and tubulointerstitial fibrosis. "GSTA3 plays a protective role against tubular EMT in renal fibrosis, suggesting GSTA3 is a potential therapeutic target for RIF." (PMID 27602565, 2016). "GSTA3 has a protective effect on Tubular epithelial-mesenchymal transition in renal fibrosis." (PMID 36762111, 2023).
breast carcinoma (1 paper, 2020). "GSTA3 overexpression in breast cancer cells stimulates proliferation and inhibits apoptosis, which leads to chemotherapy resistance and radiation resistance in tumour cells." (PMID 33024640, 2020).
colitis (1 paper, 2024). Inflammation of the colon. "We found that colitis significantly decreased GST classes alpha, mu, and pi (GSTA3, GSTM1, GSTP1)." (PMID 38668322, 2024).
conotruncal heart defects (1 paper, 2021). "GSTA3 acts by mitigating oxidative stress in the transsulfuration pathway, which is subsequently associated with increased risk of conotruncal heart defects." (PMID 33684136, 2021). "Our findings suggest that GSTA3 might play a similar role in OHD risk as that observed for conotruncal heart defects, although further studies are warranted." (PMID 33684136, 2021).
dyslipidaemia (1 paper, 2025). "Our study confirmed key proteins (PCSK9, ANGPTL3, LPA), identified potential novel targets (GSTA1, GSTA3, EPPK1, PECR, and PLA2G15), and strengthened evidence for CELSR2 and GAS6 in dyslipidaemia." (PMID 40689090, 2025).
kidney damage (1 paper, 2018). "In our study, the observed decrease in expression of GSTA3 in 7 day hypobaric hypoxia exposure rat kidneys emphasizes its role in oxidative stress-induced kidney damage." (PMID 30005088, 2018).
myopia (1 paper, 2017). "Such expression changes were evident, particularly in the late myopia dataset where a wide range of genes linked with oxidative stress were either up-regulated (GPX1, GSTA3, MT-4, APOA1, OTUB, PTGDS, HSPB1, HSPB2) or down-regulated (XHD, SLC40A1, TF, SOD3, HPGDS, BCMO1)." (PMID 28852117, 2017).
thyroid cancer (1 paper, 2020). "Genes related to cytoprotection and antioxidant response (e.g., Gsta3, Gstm1, Nqo1, Gpx2), as well as the H2O2-producing gene Aox1 that is usually decreased in thyroid cancers, were all downregulated in thyroids of KO mice, as found previously in other tissues." (PMID 32961913, 2020).
type 2 diabetes mellitus (1 paper, 2015). A type of diabetes mellitus that is characterized by insulin resistance or desensitization and increased blood glucose levels. "Eleven genes in the Glutathione metabolism pathway (Gpx7, Gss, Gsta3, Gstm2, Gstm5, Gstm7, Gsto1, Gstp1, Gstt1, Gstt2 and Mgst2) were observed in type 2 diabetes mellitus." (PMID 25788156, 2015).
cancer (4 papers, 2010 to 2023). A tumor composed of atypical neoplastic, often pleomorphic cells that invade other tissues. "On the NR0B2 cell trajectory of Abcb4−/− cholangiocytes, some molecules implicated in carcinogenesis were evidenced: GSTA3, ID2, and TMEM45A, which is a transmembrane molecule considered to be oncogenic in several cancers." (PMID 39130146, 2023). "Genes potentially implicated in carcinogenesis were also discovered on this cholangiocyte trajectory: GSTA3, inhibitor of DNA binding 2, and above all, TMEM45A, a transmembrane molecule from the Golgi apparatus considered as oncogenic in several cancers." (PMID 39130146, 2023). "The global gene expression analysis also identified AP-2 regulated genes, which have an impact on sensitivity of cancer cells towards chemotherapeutic drugs and irradiation like for example the ATP-binding-cassette, subfamilyB (MDR/TAP) member 9 and GSTA3." (PMID 20459791, 2010).
tumor (4 papers, 2017 to 2024). "Studies of genetic analysis models and the mechanism of GSTA3 found that it was associated with tumour prognosis." (PMID 33024640, 2020). "Tumor mutation burden, GSTA3, and VNN2 were the highest contributing features." (PMID 36428698, 2022). "Promoter of some of the carcinogen-metabolizing genes like CYP8B1 and GSTA3 was found to be hypomethylated, specifically, in the tumor tissues of OSCC patients in India." (PMID 28174608, 2017). "CTF1 and RAPGEF3 were previously reported to be parts of gene signatures related to tumor microenvironment and immune system, with the first seen downregulated and methylated in BAP1 mutated samples; PALMD was found to have low expression in metastatic UM tissues, and GSTA3 in low-survival patients." (PMID 38339073, 2024).
renal disease (1 paper, 2016). "Taken together, these findings suggest significant interrelationships between GSTA3 expression and oxidative stress in renal disease." (PMID 27602565, 2016).
GSTA3 also shares sentences with these, for which no sentence is quoted: bacterial infection (1 paper); colon cancer (1); fibrosarcoma (1); fibrosis (1); hepatocellular carcinoma (1); Hypertension (1); hypothyroidism (1); infection (1); nasopharyngeal carcinoma (1); Obesity (1); Renal cyst (1).